PRODH (proline dehydrogenase 1)
Diseases named in the same sentence as PRODH in open-access papers (continued):
Sharing a sentence is not in itself a finding about the gene and the disease.
cancer (continued). "During this process, TSA/SAHA can induce autophagy and apoptosis simultaneously, however interestingly, PRODH did not promote the antiproliferative effects of HDAC inhibitors on cancer cells, but induced protective autophagy and suppressed apoptosis instead." (PMID 38023181, 2023). "Although closely related to the development of cancer, currently, there are no drugs available that specifically target proline catabolism or PRODH." (PMID 38023181, 2023). "In this context, it has been reported that proapoptotic genes, including FOS, FAH, and PRODH, are upregulated in the cancer cells of nonangiogenic NSCLC." (PMID 35267627, 2022). "Probably in cancer cells, collagen biosynthesis modulates proline availability for PRODH/POX." (PMID 33818628, 2021). "In this review, we suggest that amino acid metabolism linking TCA and Urea cycles affect PRODH/POX-dependent apoptosis/autophagy and the knowledge might be useful to targeted cancer therapy." (PMID 31933109, 2020). "We also upregulated and downregulated PRODH in RM-1 cells, and found that the change of PRODH expression did not affect cancer cells growth." (PMID 30545412, 2018). "Exploration of whether these genes (HTR2A, COMT, PRODH) may influence immune cell differentiation through the immune pathways would provide interesting and plausible evidence for the correlation between SCZ and cancers." (PMID 37564635, 2023). "Furthermore, it was observed that chromatin remodeling factor LSH activated PRODH to decrease proline level to induce EMT in NSCLC, proving that PRODH could rescue the metastatic cancer cells from the nutrient stress through enhanced proline catabolism." (PMID 36998464, 2023). "Even in the same type of cancer, the role of PRODH is not singular or fixed." (PMID 38023181, 2023). "Therefore, we suggest that the role of PRODH/POX in the apoptosis/survival of cancer cells is not a zero-one system but rather depends on metabolic context of a specific cell type." (PMID 35216470, 2022). "Since LA generated in cancer cells due to Warburg effect inhibits PRODH/POX, limiting its function (apoptosis/autophagy), it seems that inhibition of Warburg effect (lactate production, e.g., by metformin) contributed to up-regulation of PRODH/POX -induced apoptosis in cancer cells." (PMID 34944532, 2021). "Thus, the proline cycle enzymes PRODH and PYCR1 are emerging cancer therapy targets." (PMID 33109600, 2020). "Additionally, another study found that the expression of PRODH under hypoxia is dependent on AMPK activation, rather than the critical transcription factors HIF-1α or HIF-2α, which are known to be overexpressed in response to hypoxia in cancer." (PMID 38023181, 2023).
infection (11 papers, 2015 to 2025). The state of being infected such as from the introduction of a foreign agent such as serum, vaccine, antigenic substance or organism. "Overexpressing some genes (Pro deaminase, PRODH, key enzymes that catalyze proline metabolism) in A. thaliana caused an obvious increase in the resistance to pathogen infection." (PMID 34868158, 2021). "Recent studies have shown that ProDH activity is upregulated in response to pathogen infection and contribute to HR and disease resistance, which apparently potentiates the accumulation of ROS." (PMID 37287445, 2023). "In some cases, pathogen infection increased the ProDH transcript level and enhanced proline catabolism triggered proline-P5C-proline cycle between mitochondria and cytosol." (PMID 26217357, 2015). "In summary, both experimental systems enable ProDH induction and apparently subsequent Pro synthesis, triggering less pronounced amino acid changes at late infection stages than in response to Pro treatment." (PMID 26284090, 2015). "To address this issue, we analyzed how P5CDH affects the activation of Pro synthesis, in Arabidopsis tissues that increase ProDH activity by transient exposure to exogenous Pro, or infection with Pseudomonas syringae pv." (PMID 26284090, 2015). "Proline catabolism pathway mediated by ProDH enzyme in mitochondria is one of the sources of mitochondrial ROS during avirulent pathogen infection in A. thaliana and the ROS produced at the infection site leads to oxidative burst thereby initiates HR." (PMID 26217357, 2015).
psychiatric disorder (8 papers, 2016 to 2025). A disorder characterized by behavioral and/or psychological abnormalities, often accompanied by physical symptoms. "PRODH has been associated with different psychiatric disorders that are characterized by alterations in social behavior." (PMID 28331058, 2017). "The 22q11.21 rCNV associated with “Any psychiatric disorder” in this study duplicates genes plausibly altering brain function: USP18, DGCR6, and PRODH." (PMID 41510264, 2025).
metabolic disorders (3 papers, 2016 to 2021). "Hyperprolinemia type I (HPI) is an autosomal recessive metabolic disorder caused by defects in proline oxidase (POX, EC: 1.5.99.8), also called proline dehydrogenase (PRODH)." (PMID 34285201, 2021).
adenocarcinoma (2 papers, 2022 to 2024). A common cancer characterized by the presence of malignant glandular cells. "We then investigated endogenous PRODH expression in adenocarcinoma cell lines and the consequences of ectopically modulating its expression." (PMID 38255788, 2024).
PRODH also shares sentences with these, for which no sentence is quoted: renal carcinoma (5 papers); bipolar disorder (3); glioblastoma (3); neuroblastoma (3); autism (2); Depression (2); lactic acidosis (2); lung squamous cell cancer (2); 22q11.2 Duplication Syndrome (1); aminoacylase 1 deficiency (1); Angelman syndrome (1); aspartylglucosaminuria (1); autism spectrum disorder (1); benign prostatic hyperplasia (1); biotinidase deficiency (1); bladder cancer (1); brain cancer (1); brain glioblastoma (1); cervical cancer (1); cervical squamous cell carcinoma (1); cognitive deficits (1); deafness (1); dimethylglycine dehydrogenase deficiency (1); diseases of the larynx and vocal cords (1); endometrial cancer (1); hemochromatosis (1); insomnia (1); Intellectual disability (1); kidney damage (1); kidney tumors (1).
A further 16 diseases each share a sentence with PRODH in 1 paper.